PTGES2 (prostaglandin E synthase 2)
Description:
Isomerase that catalyzes the conversion of PGH2 into the more stable prostaglandin E2 (PGE2) (in vitro). The biological function and the GSH-dependent property of PTGES2 is still under debate. In vivo, PTGES2 could form a complex with GSH and heme and would not participate in PGE2 synthesis but would catalyze the degradation of prostaglandin E2 H2 (PGH2) to 12(S)-hydroxy-5(Z),8(E),10(E)-heptadecatrienoic acid (HHT) and malondialdehyde (MDA) (By similarity).
Synonyms: mPGES-2; C9orf15; PGES2; FLJ14038; GBF-1
Tractability: Small molecule: a high-quality ligand is known. Antibody: its Gene Ontology location is reachable by antibodies, with high confidence; UniProt predicts a signal peptide or a membrane-spanning region. PROTAC: ubiquitination databases record sites on it; its protein half-life has been measured; a small molecule that binds it is known.
Target class: Enzyme
Gene: Protein-coding gene on chromosome 9 (128,120,693 to 128,128,462, reverse strand). Ensembl gene ENSG00000148334.
Subcellular location: Golgi apparatus membrane; Cytoplasm, perinuclear region (Prostaglandin E synthase 2 truncated form)
Pathways (Reactome):
Immune System: Neutrophil degranulation
Metabolism: Synthesis of Prostaglandins (PG) and Thromboxanes (TX)
Gene Ontology:
Molecular function: 12-hydroxyheptadecatrienoic acid synthase activity; lyase activity; prostaglandin-E synthase activity; protein binding; glutathione binding; heme binding; DNA binding
Biological process: lipid metabolic process; prostanoid biosynthetic process; cyclooxygenase pathway; prostaglandin biosynthetic process
Cellular component: cytosol; Golgi membrane; mitochondrion; azurophil granule lumen; extracellular region; nucleus; perinuclear region of cytoplasm
Genetic constraint (gnomAD): Loss-of-function variants: 34 observed, 38.22 expected, observed/expected ratio (o/e) 0.89, 90% interval 0.68 to 1.18. The upper end of that interval is the gene's LOEUF score, 1.18, which puts it in group 5 of 6, group 1 being the genes least tolerant of losing a copy. Missense variants: 478 observed, 433.13 expected, observed/expected ratio (o/e) 1.1, 90% interval 1.02 to 1.19. Synonymous variants: 203 observed, 180.74 expected, observed/expected ratio (o/e) 1.12, 90% interval 1 to 1.26.
Homologues: Orthologues: chimpanzee PTGES2 (100% identical), macaque PTGES2 (98% identical), chimpanzee PTGES2 (95% identical), dog PTGES2 (88% identical), pig PTGES2 (86% identical), guinea pig PTGES2 (84% identical), rat Ptges2 (83% identical), mouse Ptges2 (82% identical), tropical clawed frog ptges2 (59% identical), zebrafish ptgesl (58% identical), Drosophila melanogaster Su(P) (36% identical), Caenorhabditis elegans pges-2 (36% identical).
Diseases named in the same sentence as PTGES2 in open-access papers:
PTGES2 is named in the same sentence as 39 diseases in open-access papers, as found by Europe PMC text mining. Sharing a sentence is not in itself a finding about the gene and the disease. The quoted sentences say what the papers report.
endometrial cancer (4 papers, 2011 to 2024). Primary or metastatic malignant neoplasm involving the endometrium (mucous membrane that lines the endometrial cavity). "The expression of mPGES-1 is highly expressed in human epithelial ovarian cancer and cervical cancer, while PTGES2 is associated with the endometrial carcinoma carcinogenesis." (PMID 32363546, 2020). "In our study, we selected 119 samples from endometrial cancer patients, with 50 normal endometrium tissue samples as controls, in which we examined the expression of PTGES2." (PMID 27230680, 2016). "Stable PTGES2-shRNA transfectants were generated in Ishikawa and Hec-1B endometrial cancer cell lines, and transfection efficiencies were confirmed by RT-PCR and Western blot analyses." (PMID 27230680, 2016). "PTGES2 expression was high in these human endometrial cancer cell lines, with the highest levels in Ishikawa cells." (PMID 27230680, 2016). "We initially selected human endometrial cancer cells in which we performed stable depletion of PTGES2 for subsequent experiments." (PMID 27230680, 2016). "We also examined the expression of PTGES2 in several human endometrial cancer cell lines, with protein from normal endometrium (NE) as control." (PMID 27230680, 2016). "In our study, first we showed that PTGES2 is highly expressed in endometrial cancer both in tissue and in cell lines." (PMID 27230680, 2016). "Both immunohistochemistry (IHC) and Western blot analyses demonstrated that synthase PTGES2, which is required for PGE2 synthesis, was highly expressed in endometrium cancer tissues compared with normal endometrium." (PMID 27230680, 2016).
colorectal cancer (3 papers, 2025). A primary or metastatic malignant neoplasm that affects the colon or rectum. "Here, we found prostaglandin E synthase 2 (PTGES2), one key enzyme catalyzing the synthesis of prostaglandin E2, which was associated with the progression of some tumors, such as colorectal cancer (CRC), hepatocellular carcinoma (HCC), and RCC." (PMID 41041304, 2025). "For example, artemisinin has been shown to bind to microsomal prostaglandin E synthase-2 (mPGES-2), thereby reducing PGE2 production and suppressing colorectal cancer cell proliferation." (PMID 40943352, 2025).
adenomyosis (2 papers, 2021 to 2023). The growth of endometrial tissue inside the muscular wall of the uterine corpus. "Preliminary data from in vitro studies show that cells from adenomyotic lesions have higher mRNA concentrations of prostaglandin E synthase 2 (PTGES2)- the enzyme responsible of PGE2 synthesis- compared to eutopic endometrial cells from those without adenomyosis." (PMID 36304053, 2021). "In vitro studies examining cells from adenomyotic lesions reveal higher mRNA concentrations of prostaglandin E synthase 2 (PTGES2), the enzyme responsible for PGE2 synthesis, compared to eutopic endometrial cells from those without adenomyosis." (PMID 37225518, 2023).
breast carcinoma (2 papers, 2017 to 2021). "Using PROGgeneV2 webtool, we found the high expression of cMYC, KLF4, and PTGES2 are associated with poor survival whereas the high expression of PTGDS is associated with better survival in patients with breast cancer." (PMID 33494773, 2021). "Further analysis in MDA-MB-436 and Hs578T breast cancer cells showed that the expression of cMYC restores the miR-155 knockdown-induced reduction in PTGES2 promoter activity." (PMID 33494773, 2021).
colon cancer (2 papers, 2011 to 2022). "Finally, colon cancer cells show increased lipid droplet numbers which are highly enriched in cyclooxigenase-2 (COX2) and prostaglandin E synthase 2 (PGES2)." (PMID 36361914, 2022).
cutaneous melanoma (2 papers, 2020 to 2024). A primary melanoma arising from atypical melanocytes in the skin. "Similarly, BCC, malignant neoplasms of skin, and body-mass index (BMI, a quantitative endpoint) showed significant associations with PTGES2 as the top three most significant phenotypes in the UKB-PPP (9,621 protein-phenotype pairs) and deCODE (9,620 protein-phenotype pairs) studies." (PMID 39035989, 2024).
diabetes (2 papers, 2012 to 2023). "The results revealed multiple modes in which diet and diabetes affected gene expression in the placenta at E10.5: Ptges2 (encoding prostaglandin E synthase 2) was responsive to diet only in normal dams, such that breeder diet was associated with lower expression." (PMID 22701643, 2012). "Furthermore, they concluded that microsomal PTGES-2 promotes aging of β-cells and their hypofunction via the PGE/EP3/NR4A1 axis, and drug blocking of microsomal PTGES-2 might have a therapeutic effect on aging-induced beta cellular hypofunction and diabetes." (PMID 37867507, 2023).
endometrial adenocarcinomas (1 paper, 2011). "We found elevated expression of PTGES2 and PTGER4 and suppression of PTGER1 and PTGER3 in endometrial adenocarcinomas compared with normal endometrium." (PMID 21589857, 2011). "We found elevated expression of PTGES2 (P<0.01) and PTGER4 (P<0.01) in all grades of endometrial adenocarcinomas compared with pooled normal endometrium." (PMID 21589857, 2011). "Here we investigated (a) the expression profile of the PGE synthase enzymes (PTGES, PTGES-2, PTGES-3) and PGE receptors (PTGER1–4) in endometrial adenocarcinomas compared with normal endometrium and (b) the role of PTGER4 in endometrial tumorigenesis in vivo." (PMID 21589857, 2011). "Here, we show suppression of PTGER1 and PTGER3 and elevated expression of PTGES2 and PTGER4 in endometrial adenocarcinomas compared with normal endometrium." (PMID 21589857, 2011).
endometrial tumour (1 paper, 2011). "The suppression of these receptors and augmentation of PTGER4, strongly suggest that PGE2, produced via PTGS and PTGES2, is a driver of endometrial tumour development via the activation of PTGER4 and initiation of cAMP signalling." (PMID 21589857, 2011).
hypothyroidism (1 paper, 2021). Abnormally low levels of thyroid hormone. "This suggests that hypothyroidism may stimulate the synthesis of PTGES2 and inhibit the synthesis of PGFS but does not affect the synthesis of PTGES-3 or PGIS." (PMID 34573602, 2021).
Insulin resistance (1 paper, 2020). Increased resistance towards insulin, that is, diminished effectiveness of insulin in reducing blood glucose levels. "PTGES-2, also known as cyclooxygenase-2, has in fact been shown to be linked to the early onset of type 2 diabetes and insulin resistance in chronic low-grade inflammation state, especially through the production of PGE2." (PMID 31947646, 2020).
ischemia (1 paper, 2023). A hypoperfusion of the BLOOD through an organ or tissue caused by a PATHOLOGIC CONSTRICTION or obstruction of its BLOOD VESSELS, or an absence of BLOOD CIRCULATION. "Furthermore, fewer TUNEL-positive cells were found in the kidneys of Ptges2-/- mice compared to that in Ptges2+/+ mice subjected to renal unilateral ischemia/reperfusion." (PMID 37907523, 2023).
melanoma (1 paper, 2020). A malignant, usually aggressive tumor composed of atypical, neoplastic melanocytes. "Amplification or overexpression of PTGES/PTGES2 in melanoma samples was associated with a significantly lower patient survival, emphasising the significance of our findings." (PMID 31819183, 2020).
nephrosclerosis (1 paper, 2023). Hardening of the kidney due to infiltration by fibrous connective tissue (fibrosis), usually caused by renovascular diseases or chronic hypertension. "We aimed to determine whether genetic variability represented by 38 tag-SNPs in genes of the cyclooxygenase pathway (PTGS1, PTGS2, PTGES, PTGES2 and PTGES3) leading to prostaglandin E2 (PGE2) synthesis, modified CV traits and events in 493 nephrosclerosis patients." (PMID 36690661, 2023).
Obesity (1 paper, 2020). Accumulation of substantial excess body fat. "In obesity, PTGES-2 promotes adipose tissue dysfunction, with sustained inflammation and fibrosis, impaired adaptative thermogenesis and increased lipolysis." (PMID 31947646, 2020). "In view of the role PTGES-2 in obesity and in the control of intracellular cAMP concentrations through PGE2 receptors, we investigate the possible association between PTGES-2 and EPAC2 cAMP effector and ST2/IL-33 mechanosensitive genes." (PMID 31947646, 2020).
osteoarthritis (1 paper, 2024). A noninflammatory degenerative joint disease occurring chiefly in older persons, characterized by degeneration of the articular cartilage, hypertrophy of bone at the margins and changes in the synovial membrane. "The progression involves the NF-κB signaling pathway, triggered by IL-1β, affecting the enzymes linked with pathophysiology of osteoarthritis, including iNOS, PLA2, COX-2, prostaglandin E synthase 2 (PGE2 synthase), and MMPs." (PMID 39204123, 2024).
pancreatic tumors (1 paper, 2023). "A similar expression pattern was noted for the PTGES2 protein in pancreatic tumors." (PMID 37108468, 2023).
sarcopenia (1 paper, 2023). Progressive decline in muscle mass due to aging which results in decreased functional capacity of muscles. "Nevertheless, in patients with sarcopenia, we noticed a significant negative correlation between the mRNA level of PTGES2 and PTGS2 and serum creatine kinase (CK) concertation." (PMID 37629065, 2023). "The mRNA level of PTGES2 was significantly the lowest in healthy subjects at the age of 25–30 years in comparison with geriatric control, patients with frailty syndrome and sarcopenia, but not healthy subjects at age above 50 years." (PMID 37629065, 2023). "Patients with frailty syndrome revealed a lower expression of PTGES2 than geriatric control and patients with sarcopenia; however, the difference was not statistically significant." (PMID 37629065, 2023). "Additionally, in patients with sarcopenia, a negative correlation was also observed between creatine phosphokinase and the expressions of PTGES2 (COX2) and PTGS2." (PMID 37629065, 2023).
skin cancer (1 paper, 2024). "PTGES2, RNASET2, SF3B4, and STX8 showed significant associations with skin cancer after FDR correction." (PMID 39035989, 2024). "Interestingly, PTGES2, RNASET2, SF3B4, and STX8, associated with skin cancer risk, were also significantly associated with NMSC and BCC risks." (PMID 39035989, 2024). "Furthermore, prostaglandin E synthase 2 (PTGES2), ribonuclease T2 (RNASET2), SF3B4, and STX8 were significantly associated with skin cancer risk after FDR correction for multiple testing (FDR <0.05)." (PMID 39035989, 2024).
cancer (11 papers, 2015 to 2025). A tumor composed of atypical neoplastic, often pleomorphic cells that invade other tissues. "The synthesis of PGE2 was an extremely complicated process; one targeted metabolite profiling uncovered that PTGES2 was the key enzyme, and PTGES2 was confirmed to influence the survival of cancer cells." (PMID 41041304, 2025). "This analysis confirmed that PTGS2 and PTGES2 are the central genes through which aspirin impacts cancer survival." (PMID 38201650, 2024). "For the CRC cells, while elevated PTGES2 led to PGE2 boosting, reactive oxygen species (ROS) were largely produced, and genomic instability was triggered, ultimately driving cancer progression." (PMID 41041304, 2025). "We found that IFNA1 and IFNL1 gene transcripts resulted negligibly expressed across the pan-cancer dataset when compared to other immunosuppressive and pro-inflammatory cytokines such as TGFB1/2, PTGES2, IL1A, IL1B, IL6 and CSF1." (PMID 38239354, 2023). "PGE2, known for inducing immunosuppression and promoting M2 macrophage polarisation, showed no change in expression, with Ptges2 unaffected by cancer cell medium or infection." (PMID 40547518, 2025). "Notably, MpEV-ATMSC showed the upregulation of PTGES2 and COX2, two factors responsible for PGE2 production, and the secretion of PGE2 which are known to be involved in the interaction between TA-MSC and cancer cells." (PMID 38515582, 2024). "According to GEPIA, only four types of cancers have increased expression of mPGES-2/PTGES2, which shows that this enzyme may not be cancer-specific." (PMID 36765904, 2023).
tumor (11 papers, 2015 to 2025). "Interestingly, 5.5% of patients had tumours with amplification of PTGES or PTGES2 or increased expression of the mRNAs they encode." (PMID 31819183, 2020). "The network of PTGS2 and PTGES2 with tumor suppressor genes showed nearly 70% physical interactions with 21 secondary nodes between these genes." (PMID 38201650, 2024). "Further, qPCR analysis of normal appearing colonic mucosa and tumor samples showed that the expression of β-catenin and NF-κB downstream gene targets (Ptges2, Nos2, and Ccnd1) were greater in 28Si exposed mice relative to control and γ radiation groups." (PMID 36584137, 2022). "Additionally, targeting PTGES2 reduces prostaglandin E2 synthesis, which promotes tumor growth and angiogenesis." (PMID 41463227, 2025). "To further investigate the effects of DCS on inflammation, we measured inflammation‐related protein expression of IKBα, p‐NF‐κB, NF‐κB, prostaglandin E synthase 2 (PTGES2) and cyclooxygenase‐2 (COX‐2), in NCI‐H460 cells and tumour tissue." (PMID 28444871, 2017). "In particular, our analysis revealed increased expression of various immune modulatory molecules (CD274 (PD-L1), OSM, PTGES2, CD36, and MSR1) by tumor-infiltrating monocytes and neutrophils suggesting an immune suppressive role is adopted following infiltration into the TME." (PMID 39932553, 2025).
infection (3 papers, 2008 to 2025). The state of being infected such as from the introduction of a foreign agent such as serum, vaccine, antigenic substance or organism. "Among the differentially expressed genes, four genes, Il1, Il1rn, Ptges, and Ptges2, showed marked up regulation in susceptible strains, while showed no change or slight decrease in levels in resistant strains post-infection." (PMID 18421376, 2008).
neurodegenerative disease (2 papers, 2013 to 2020). A disorder of the central nervous system characterized by gradual and progressive loss of neural tissue and neurologic function. "Increasing evidence has demonstrated that microglial activation and the consequent release of proinflammatory and cytotoxic factors such as TNFα, IL-1β, NO, and prostaglandin E synthase 2 (PGE2) are thought to contribute to the neurodegenerative diseases." (PMID 24349614, 2013).
PTGES2 also shares sentences with these, for which no sentence is quoted: COVID-19 (3 papers); acute kidney injury (1); adenocarcinoma (1); basal cell carcinoma (1); cervical cancer (1); dyslipidemia (1); epithelial ovarian cancer (1); Fungal Infection (1); hepatocellular carcinoma (1); hypogonadotropic hypogonadism (1); pneumonia (1); psoriasis (1); Sepsis (1); type 2 diabetes (1); type-1 diabetes (1); uveal melanoma (1).